CD4 (CD4 molecule)
Diseases named in the same sentence as CD4 in open-access papers (continued):
Sharing a sentence is not in itself a finding about the gene and the disease.
tumor (continued). "Cellular and proteomic changes were detected in the tumor microenvironment, including enhanced cytotoxicity of effector populations such as CD4+, CD8+ T cells, natural killer, and natural killer T cells." (PMID 40589567, 2025). "We validated the increased T cell infiltrate via IHC in the β-M model demonstrating increased CD3+ and CD4+ cells within tumor nodules with organization into lymphoid aggregates (LA) in the β-M R animals." (PMID 40442146, 2025). "Overcoming these repressive mechanisms enhances MHC‐II expression in AML cells, thereby stimulating CD4+ T cell activation and anti‐tumour responses." (PMID 40673641, 2025). "This spatial dichotomy enables CD4 T cells to act as functional allies of the tumor, delivering trophic and immunomodulatory cues, while TAMs maintain a suppressive environment that hinders effective cytotoxic responses." (PMID 41256864, 2025). "Cxcr3 expression was relatively specific to CD4+ T cells and increased following anti-PD-L1 treatment, and an increase in CD4+ T cells was evident in the tumour core in anti-PD-L1-treated tumours." (PMID 40523200, 2025). "We then asked what is the contribution of the stage-specific expression of Bcl-6 relative to T-bet to the anti-tumor CD4+ T-cell response to M002 treatment." (PMID 39885128, 2025). "These systems lead to Damage-associated molecular patterns (DAMPs) and tumor antigens are released as a result of immunogenic cell death (ICD), which promotes dendritic cell maturation and CD4+ T-cell priming." (PMID 40860882, 2025). "The microenvironment of tumor seeded with V583 demonstrated increased density of CD4+ (49.85 vs 16.46 cells/mm2, p = 0.02 unpaired t-test) and CD4 + FoxP3+ (4.85 vs 1.81 cells/mm2, p = 0.04) cells in the tumor microenvironment." (PMID 41322090, 2025). "In any case, the high percentage of CD4+ Tregs in untreated controls is a likely driver of tumor resistance, and their reduction relative to CD8+ T cells is essential to a robust antitumor response." (PMID 40813233, 2025). "Our analysis yielded significant findings, demonstrating a notably higher abundance of tumor-reactive B cells, CD4, CD8 T cells, and dendritic cells in responder patients compared to their non-responder counterparts." (PMID 40287406, 2025). "Tregs, a specialized subset of CD4+ T cells, frequently accumulate and overactivate in carcinomas, contributing to immunosuppression and tumor immune escape." (PMID 40977743, 2025). "Emerging therapeutic strategies targeting CD4+ T cells include blockade of IL-17 signaling to counteract Th17-driven tumor progression, and the development of CD4+ T cell-based vaccines and adoptive T cell therapies." (PMID 41244711, 2025). "Researchers have identified HLA-I-binding antigenic peptides from tumor-specific circRNAs, circFAM53B, which effectively primed naive CD4+ and CD8+ T cells and induced anti-tumor immunity." (PMID 39944685, 2025). "Lung CD8+ cells from CD4-depleted MMTV-Her2 mice after IAV infection had superior killing activity against HER2+ tumour cells compared with lung CD8+ cells from IAV-infected Her2 mice." (PMID 40739350, 2025). "At the tumor T cell level, there was a significant increase in CD4+ cells and CD8+ cells, as well as activated IFN-γ+CD8+ T cells in the combination therapy group." (PMID 41383334, 2025). "For RKIP, higher expression was associated with reduced infiltration of regulatory T cells and memory CD4 + T cells while positively correlated with mast and NK cells which are both involved with anti-tumor responses." (PMID 41327312, 2025). "The dietary uptake of inulin inhibited tumor growth via the activation of both CD8 + T and CD4 + T cells, these cells play an important role in inducing anti-tumor immune responses." (PMID 39858007, 2025). "Through cytokine secretion and direct interactions with immune and tumor cells, CD4+ T cells play a pivotal role in the tumor immune response by influencing the composition and activity of the tumor immune microenvironment." (PMID 40176817, 2025).
tumor (continued). "This improves CD4+ T cell activation, triggering tumor-specific CTL expansion and limiting OSCC growth." (PMID 40724900, 2025). "Although CD8+ T cells are widely recognized for their cytotoxic function, CD4+ T cells also play an essential role in tumor control." (PMID 40430079, 2025). "Multiple immunocompetent tumor models: It can directly activate macrophages and promote the recruitment and activation of CD4+ and CD8+T lymphocytes in TME." (PMID 40161377, 2025). "In this study, we demonstrated that DSF, as an inhibitor of GSDMD-N oligomerization, promoted tumor growth by suppressing CD4+ T cell–mediated antitumor immunity." (PMID 40759573, 2025). "In lung and cervical tumor samples, Erα signaling is associated with reduced infiltration of CD4+ and CD8+ T cells into the tumor microenvironment." (PMID 41200178, 2025). "Tumour CD4+ T-cell results were consistent with these outcomes for haemoglobin and haematocrit Pre-Cycle 2 and End chemo." (PMID 40468999, 2025). "A relative decrease in the proportion of CD4+ cells in tumor tissues was observed, whereas the proportions of CD8+ cells, NK cells, and Treg cells experienced various increments." (PMID 40723292, 2025). "The T cell compartment demonstrated a notable shift, with significantly elevated levels of activated CD4+ memory T cells and reduced levels of resting CD4+ memory T cells in tumor tissues." (PMID 39940699, 2025). "Researchers compared changes in T cells within TDLNs and tumor tissues of patients treated with the combined therapy, and found that TDLNs consisted mainly of initial/central memory CD4+ T cells, whereas tumors were dominated by Teff." (PMID 40385461, 2025). "Previous studies have shown that CD4+ T-cells secrete cytokines to support anti-tumor immunity generated by CD8+ T-cells." (PMID 39963131, 2025). "Heat-inactivated OpdA significantly reduced metastasis, dependent on tumor-specific CD4+ and CD8+ T cells and IFN-γ, both locally and systemically, with decreased IL-10 levels suggesting a proinflammatory environment." (PMID 41019059, 2025). "We found that in the absence of CCR9, there is a significant increase of CD8+ T cells recruited to both the tumor and peri-tumoral zone zones and therefore, with a concomitant decrease in the frequencies of CD4+ T cells, as expected." (PMID 40305493, 2025). "Tumor antigens, after being captured by DCs, migrate to TDLNs and are presented to naive CD4+ T cells via MHC II proteins, initiating their activation and differentiation programs." (PMID 40904508, 2025). "In NSCLCs, tumor infiltrating CD8+ T-cells or CD4+ that simultaneously express CD39 are characterized by a strong anti-tumor reactivity and have a high probability to react with neo-antigens of the tumor." (PMID 40227655, 2025). "Under GMP settings, clinical experiments employing MHC II aAPCs show that tumor-specific CD4+ T cells can grow safely." (PMID 40860882, 2025). "Tregs are another important T cell subset that can differentiate into effector CD4 T cells and amplify tumor immunosuppression." (PMID 40641743, 2025). "Combined production of TNF-α and IFN-γ from CD4 T cells has been shown to alter the tumor microenvironment sensitizing tumors to various types of chemotherapy, such as treatment with cyclophosphamide and 5-fluorouracil." (PMID 40429884, 2025). "Here, we aimed to confirm the pharmacodynamic effects of MBE1 in vivo using tumor models that were previously validated to depend on ALDH1A3 for suppression of CD4 T cells." (PMID 41210994, 2025). "As a representative species, Akkermansia muciniphila has been shown to restore the efficacy of PD-1 blockade in an interleukin-12-dependent manner by increasing the recruitment of CCR9+CXCR3+CD4+ T cells into the tumor microenvironment." (PMID 41304278, 2025). "This along with a greater CD4+ T‐cell interaction with B cells in IL17A−/− tumours suggests an enhanced humoral response and B‐cell activation." (PMID 40831074, 2025).
tumor (continued). "By utilizing a preclinical murine model, we have developed a novel ex vivo expansion model of tumor-primed effector CD4+ T cells." (PMID 40563574, 2025). "Higher infiltration of CD4+ T cells, crucial for anti-tumor immunity, was observed in fibrosis, and in the IM and NTT regions of HCC liver." (PMID 40698077, 2025). "At the level of the lamina propria of tumor tissue, a significantly greater percentage of CD4+ and CD8+ T cells was detected in Mgl1−/− CAC mice than in WT CAC mice." (PMID 40033767, 2025). "In-depth functional immune cell analyses revealed a dominant CD4+ T-cell response against the vaccine antigens with infiltration of the tumor site and immune responses prevailing for years following the last vaccine administration." (PMID 41067882, 2025). "No significant changes in the population of neutrophils (CD45+CD3‐CD11b+Ly6G+), B cells (CD45+CD3‐CD19+) or Tregs (CD45+CD3+CD4+FOXP3+) were observed in the tumor TME following anti‐MARCO treatment or its combination with PD‐1 mAbs." (PMID 41117057, 2025). "This spatially resolved approach advances beyond conventional immunohistochemistry by precisely mapping topological relationships between CD4+ T cells and NK cells, offering three-dimensional insights into tumor immune microenvironment heterogeneity." (PMID 40510347, 2025). "In the vaccine-treated group, both CD8+ and CD4+ T cells increased at the tumor site, with an elevated secretion of the cytotoxic mediator IFN-γ." (PMID 39888994, 2025). "In another study, real‐time imaging captured antigen presentation by DCs to CAR CD4+ T cells at the invasive tumor margin." (PMID 40257446, 2025). "One key factor contributing to the limited efficacy of previous anticancer vaccine trials is the insufficient stimulation of tumor-reactive CD4+ T cells." (PMID 40543509, 2025). "Further enhances the M1-like polarization of TAMs and amplifies the activation of CD8+ T cells and Th1 CD4+ T cells, along with reduced tumor growth." (PMID 40330466, 2025). "The findings suggested that lower CD4 T cell count was more likely to be related to advanced tumor burden." (PMID 40969752, 2025). "On one hand, TNFRSF9 can augment CD8 + T cell-mediated tumor-related immune responses by boosting the immune functions of CD4 + T and NK cells." (PMID 40072746, 2025). "Oncolytic virus can reduce the number of FoxP3+CD4+ T cells in the tumor microenvironment and facilitate the polarization of M2 macrophages into M1 macrophages." (PMID 40352942, 2025). "This group also showed higher levels of anti-tumor immune cells, such as activated CD4 and CD8 T cells and NK cells." (PMID 39857718, 2025). "The sustained increase of Bcl-6 to T-bet secondary to the deletion of T-bet in CD4+ T cells was deleterious to anti-tumor responses, and reduced Bcl-6 expression at the early stage of treatment only produced some survival benefit." (PMID 39885128, 2025). "Most MDV-transformed tumor cells consist of CD4+ T-cells, indicating oligoclonal expansion of transformed CD4+ T-cells." (PMID 40430752, 2025). "CD4+ T lymphocytes can differentiate into subgroups such as Th17 and Treg, participating in the immune response regulation of tumor microenvironment." (PMID 40417009, 2025). "This treatment not only effectively suppressed tumor growth and promoted anti-tumor immunity but also enhanced the generation of memory CD4+ and CD8+ T cells, thereby facilitating the establishment of immune memory." (PMID 40698137, 2025). "We found that CD11b+Gr-1+ cells isolated from PBS- or NPempty-treated tumor-bearing mice strongly suppressed both CD4+ and CD8+ T cell proliferation (74.86-80.78% for CD4+ T cells, 76.64 -81.1% for CD8+ T cells)." (PMID 40134427, 2025). "Our results disclosed that tumors with high-risk scores tended to have comparatively high tumor infiltration of neutrophils, macrophages, and CD4+ T cells, while low-risk tumors typically exhibit a comparatively high level of CD8+ T cell tumor infiltration." (PMID 40182754, 2025).
tumor (continued). "Multiplexed IF staining of tumor tissues after treatment confirmed enhanced CD4 and CD8 T-cell infiltration upon treatment with the RMC-7977 + palbociclib combination at 14 days after treatment initiation." (PMID 40299790, 2025). "In the low-risk group, we observed higher levels of CD4+ effector memory T cells, CD8+ T cells, and natural killer (NK) cells, all of which are typically associated with anti-tumor immunity." (PMID 40842996, 2025). "Within TLSs, B cells function as professional antigen-presenting cells, internalizing and processing tumor-derived antigens for presentation via MHC class II molecules to CD4+ T cells." (PMID 41246318, 2025). "This increases the infiltration of CD4+/CD8+ T cells into tumor tissues and enhances the clonality of memory T cells." (PMID 40356928, 2025). "Tumor samples from all three groups contained more CD4+ T cells and Tregs than their surrounding non-tumor counterparts." (PMID 40547009, 2025). "These neoantigens can directly interact with major histocompatibility complex (MHC) molecules, activating cytotoxic CD8+ T cells and CD4+ T cells to initiate an anti-tumor immune response." (PMID 40563603, 2025). "CD4+/Foxp3+ Tregs were found embedded in the tumor mass or in the perivascular area, occasionally close to the CRATER edges but rarely inside." (PMID 41109214, 2025). "CAR4 T (CD4+ CAR-T) cells form high concentrations of IFN-γ in the tumor microenvironment to eliminate IFN-γ-sensitive tumor cells at the distal end." (PMID 40046061, 2025). "Anti-PD-L1 plus anti-CTLA4 early response in HNSCC is characterized by CD4+ T cell activation and recruitment from tumor-draining lymph nodes." (PMID 40661938, 2025). "Blocking IL-33 or its receptor ST2 inhibits Th9 differentiation from CD4+ T cells, underscoring the importance of this pathway in anti-tumor responses." (PMID 41163402, 2025). "This discovery challenges the traditional view of CD4+ T cells as mere helpers and places them at the forefront of immune-mediated tumor killing in BC." (PMID 40177538, 2025). "B cell-mediated anti-tumor activity primarily depended on the secretion of antibodies targeting the tumor-associated antigens (TAAs) and facilitated activation of the TAA-specific CD4+ T cells through the co-stimulatory signals." (PMID 40672953, 2025). "Spatial distance analysis revealed that high tsMHC-II expression leads to closer tumor proximity to CD4 + and CD8 + T cells, indicating stronger anti-tumor potential." (PMID 40495188, 2025). "Malignant CD4 T-cells from tumor lesions exhibited a log2 fold change of −2.34 (adjusted p-value < 0.0001)." (PMID 41226451, 2025). "Deletion of TIM-3 on CD4+ and CD8+ T cells reduced tumour burden and loss of TIM-3 in DC cells enhanced antigen-specific anti-tumour immunity, expanded stem-like CD8+ cells and activation inflammasome pathways." (PMID 40038352, 2025). "The combination of more immunogenic Ptdss1KD tumor cells and proinflammatory myeloid cells likely resulted in the increase of both effector CD8+ and TH1 CD4+ T cells, predisposing Ptdss1KD tumors to improved response to anti–PD-1 therapy." (PMID 40929270, 2025). "IL-17 from CD4+ T cells supports tumor development and angiogenesis by stimulating VEGF production in cancer cells." (PMID 40297577, 2025). "IFN-γ directly promotes apoptosis in tumor cells, and CD4+ CAR-T cells can facilitate tumor killing at distant sites in an IFN-γ-dependent manner." (PMID 39981247, 2025). "In actual distances, the cell populations that displayed the largest distance were between TAMs and all other cell types (CD4+ and CD8+ T cells and CK+ tumor cells), as well as the distance between CD4+ and CD8+ T cells." (PMID 40459946, 2025). "Third, we compared the MR estimates using CD4+ T cell eQTLs from blood as instruments versus those using tumor‐tissue‐based eQTLs as instruments (data from PancanQTL database)." (PMID 41216857, 2025).
tumor (continued). "By releasing cytokines such as IFN-γ, TNF, and IL-2, CD4+ T cells further promote the differentiation and activation of macrophages, CD8+ T cells, and NK cells, while limiting tumor-associated angiogenesis, thereby reinforcing antitumor responses." (PMID 41320679, 2025). "The number of CD4+ cells in the tumor treated with the combination therapy of IQM and anti‐PD‐1 mAb was significantly higher than with the control vehicle." (PMID 40371846, 2025). "CD8+T cells, which secrete TNF-α and IFN-γ are essential effectors involved in tumor cell elimination, whereas CD4+T cells are pivotal in orchestrating the overall antitumor response." (PMID 40670983, 2025). "The repeated activation of TRPV1-positive sensory neurons reduces intra-tumour CD4+ T cells and possibly promotes tumour growth." (PMID 39940997, 2025). "CD4+ and CD8+ T cells play a crucial role in tumor immune surveillance by recognizing tumor-associated antigens (TAAs), which lead to the secretion of various cytokines and chemokines." (PMID 41246355, 2025). "These CD4+ ICOShigh IFN-γ-producing T cells demonstrated the ability to recognise tumour antigens, and their proliferation increased the ratio of effector T cells (Teffs) to regulatory T cells (Tregs) in both peripheral blood and tumour tissue." (PMID 39325360, 2025). "To investigate the association between high expression of CD40 and the T-cell costimulatory molecules CD28 or GITR in an "immunologically hot" tumor microenvironment, we performed a univariable analysis stratified by the tumor's CD4/CD8 expression status." (PMID 41182434, 2025). "CCR8+ Tregs play a crucial role in the immune-suppressive tumor microenvironment in CRC by inhibiting the function of CD4+ Th and CD8+ T cells." (PMID 40308582, 2025). "On average, Treg proportions tended to increase from blood to ascites to tumor samples, although Treg frequency was < 4% of CD4+ T cells." (PMID 41221283, 2025). "The remaining 17 tumor-enriched clones were dominated by CD4+ T cells, CD8+ T cells, or B/plasma cells." (PMID 40777278, 2025). "T cells account for most of the MDV-transformed tumor cells, indicating an oligoclonal expansion of transformed CD4+ T cells." (PMID 40673706, 2025). "Immunohistochemistry results further confirmed that tumours in the high ARM group displayed significantly reduced infiltration of CD4, CD8 and CD20 cells, indicating a more pronounced immunosuppressive microenvironment." (PMID 40736341, 2025). "Platelet PD-L1 acquired from tumor cells correlates with suppression of CD4+ and CD8+ T-cell function, and a computational model measuring platelet PD-L1 load outperforms traditional histological PD-L1 scoring in predicting ICI responsiveness in NSCLC." (PMID 40514754, 2025). "In HPV16-positive oropharyngeal cancer, CD163+ DC3s support antitumor immunity by driving CD4+ and CD8+ type I responses and cytokine production, associated with tumor-specific T cell infiltration and improved patient survival." (PMID 40584260, 2025). "Regulatory T (Treg) cells, the major subtype of the immunosuppressive cells in the tumor microenvironment, represent 10%–50% of tumor-infiltrating CD4+ T cells while only occupying 2%–5% of peripheral CD4+ T cells in healthy individuals." (PMID 40290124, 2025). "Pseudohypoxia induced by HIF-PH inhibitors activates antitumor immune responses, at least in part, through the induction of IL-2 secretion from CD4+ T cells in the spleen and tumor microenvironment, thereby enhancing immune efficacy against MSS CRC." (PMID 40343532, 2025). "The recent discovery of cytotoxic CD4+ T cells challenges the traditional view of CD4+ T cells as mere helpers and suggests new avenues for enhancing anti-tumor immunity." (PMID 40177538, 2025). "In the same model, we also found that CD4+ T cell depletion significantly reduced tumor growth in mice bearing mock-transfected B16F10 tumors; however, this effect was lost in mice bearing ULBP2-expressing tumors." (PMID 40558520, 2025).